EEA1 (early endosome antigen 1)
Description:
Binds phospholipid vesicles containing phosphatidylinositol 3-phosphate and participates in endosomal trafficking.
Synonyms: ZFYVE2; MST105; MSTP105
Tractability: Small molecule: a structure with a bound ligand is known; it has a binding pocket of medium quality. Antibody: UniProt places it where antibodies can reach, with medium confidence. PROTAC: ubiquitination databases record sites on it; its protein half-life has been measured.
Gene: Protein-coding gene on chromosome 12 (92,770,637 to 92,929,350, reverse strand). Ensembl gene ENSG00000102189.
Subcellular location: Early endosome membrane; Cytoplasm
Subcellular location (Human Protein Atlas): Vesicles
Pathways (Reactome):
Immune System: Toll Like Receptor 9 (TLR9) Cascade
Gene Ontology:
Molecular function: 1-phosphatidylinositol binding; GTP-dependent protein binding; protein binding; protein homodimerization activity; calmodulin binding; zinc ion binding; metal ion binding
Biological process: endocytosis; host-mediated perturbation of viral process; vesicle fusion; early endosome to late endosome transport; synaptic vesicle to endosome fusion; chemical synaptic transmission, postsynaptic
Cellular component: cytoplasm; cytosol; early endosome; early endosome membrane; extracellular exosome; axonal spine; cytoplasmic vesicle; endosome; glutamatergic synapse; postsynaptic early endosome; presynaptic endosome; recycling endosome; Schaffer collateral - CA1 synapse
Genetic constraint (gnomAD): Loss-of-function variants: 78 observed, 142.01 expected, observed/expected ratio (o/e) 0.55, 90% interval 0.46 to 0.66. The upper end of that interval is the gene's LOEUF score, 0.66, which puts it in group 2 of 6, group 1 being the genes least tolerant of losing a copy. Missense variants: 1,052 observed, 1,255.7 expected, observed/expected ratio (o/e) 0.84, 90% interval 0.8 to 0.88. Synonymous variants: 432 observed, 446.99 expected, observed/expected ratio (o/e) 0.97, 90% interval 0.89 to 1.05.
Homologues: Orthologues: chimpanzee EEA1 (99% identical), macaque EEA1 (99% identical), dog EEA1 (92% identical), guinea pig EEA1 (88% identical), rabbit EEA1 (87% identical), mouse Eea1 (86% identical), rat Eea1 (86% identical), pig EEA1 (80% identical), tropical clawed frog eea1 (66% identical), zebrafish eea1 (58% identical), Caenorhabditis elegans eea-1 (22% identical), Drosophila melanogaster Rbpn-5 (13% identical).
Diseases named in the same sentence as EEA1 in open-access papers:
EEA1 is named in the same sentence as 51 diseases in open-access papers, as found by Europe PMC text mining. Sharing a sentence is not in itself a finding about the gene and the disease. The quoted sentences say what the papers report.
breast carcinoma (8 papers, 2016 to 2024). "The EEC genes identified in here (with the exception of AGPAT3/4, ASTN2, and EEA1), have previously been shown to be associated with breast cancer in gene expression and functional studies." (PMID 29965997, 2018). "Metastatic breast cancer cells also tend to enter the clathrin-mediated (EEA-1-conjugated) early endosome to modulate the TGFR signaling pathways." (PMID 27830743, 2016). "Endogenous SORLA was found to localize largely to early endosomes (identified by EEA1 and Rab5 expression) and retrograde vesicles (VPS35) in MDA-MB-361 breast cancer cells." (PMID 31138794, 2019). "We began by evaluating the colocalization of MUC1 and EGFR with EEA1, a marker of the early endosome in both BT20 and MDA-MB-468 breast cancer cells." (PMID 29464085, 2018). "The effect on EEA1 and p62 was confirmed in an independent NAA30-KO breast cancer cell line." (PMID 37891180, 2023).
prostate carcinoma (5 papers, 2015 to 2022). A carcinoma that arises from epithelial cells of the prostate gland. "The expression of RAB5A and EEA1 was significantly reduced in metastatic prostate cancer when compared to primary prostate cancer tissue (P ≤ 0.05)." (PMID 26473288, 2015). "Additionally, the second gene component included EEA1 which is reported to have significantly altered expression levels in prostate cancer patients." (PMID 35882830, 2022). "In prostate cancer cell lines, ReTEGCholestanol co-localized with some Rab5-early endosomes, but not with EEA1-early endosomes." (PMID 35657681, 2022). "RT-qPCR analysis show that ADAM10, ARMC8, COMMD8, EEA1 and PPM1B were expressed at similar levels in prostate cancer cells transfected with ZBTB38 and control siRNAs suggesting that these genes are not regulated by ZBTB38, but rather co-regulated by a common upstream factor and/or pathway." (PMID 32365491, 2020). "In the current study, quantitation of gene signatures for the early endosomal genes APPL1, EEA1 and RAB5A, and analysis of the endosomal genes MYO1B, PDCD6IP and STX12 in prostate cancer patients expressing PSA ≤ 10 ng/mL, led to patient stratification into high and low-risk recurrence groups." (PMID 26473288, 2015). "The expression of APPL1 and EEA1 was significantly increased in primary prostate cancer when compared to non-malignant controls (P ≤ 0.05)." (PMID 26473288, 2015). "In addition, in non-malignant cells, both Rab5A and its effector EEA1 were concentrated in the perinuclear region, whereas in prostate cancer cells, these endosomal compartments were found throughout the cytoplasm, with some compartments located toward the cell periphery in cellular extensions." (PMID 30459931, 2018). "NOX2 co-located with Appl1, Rab5A, EEA1 and Rab7 endosome markers in non-malignant cells, but the co-location of NOX2 with these different endosome compartments was significantly increased in prostate cancer cells." (PMID 30459931, 2018).
viral infection (5 papers, 2017 to 2025). "Viral infection and PsV colocalization with EEA1 were significantly decreased when cells were treated with Cdc42 siRNA 48 h prior to viral addition." (PMID 35746622, 2022). "As shown, the virus may follow the endocytic route by colocalizing with the EEA-1 marker, only present in early endosomes, and requiring a low pH for productive infection, as viral infection dropped during treating with NH4Cl at early times." (PMID 39456165, 2024). "While approximately 38% colocalization between PRRSV and EEA1 was observed at 3 hpi, only 12% colocalization between PRRSV and LAMP-1 was observed at 3 h after virus infection." (PMID 40871241, 2025).
Cognitive impairment (2 papers, 2024 to 2025). Abnormal cognition is characterized by deficits in thinking, reasoning, or remembering. "For example, hypertrophied EEA1-positive endosomes have also been found in blood mononuclear cells and fibroblasts from patients with mild cognitive impairment or AD, as well as in mouse model brains and cultured neurons." (PMID 38999927, 2024). "Icariin can also reduce the co-localization of AβPP with the early endosome marker early endosome antigen 1 (EEA1), inhibit its entry into endosomes for cleavage by β/γ secretases to generate Aβ, thereby reducing Aβ production and improving cognitive impairment in AD mouse models." (PMID 41267743, 2025).
COVID-19 (2 papers, 2022 to 2024). A disease caused by infection with severe acute respiratory syndrome coronavirus 2. "Scaled PhIP-seq examination of both MIS-C and KD demonstrated rare, overlapping antigens, including CGNL1, as well as several strongly enriched putative pneumonia-associated antigens in severe COVID-19, including the endosomal protein EEA1." (PMID 36300623, 2022). "While intriguing, future studies will be needed to determine whether the specificity of EEA1 autoantibodies to severe-critical COVID-19 can be replicated in independent cohorts, as well as in orthogonal assays." (PMID 36300623, 2022). "Others also found that the EEA1 gene residing in an associated locus linked to COVID-19 disease severity suggests an overactive cellular response that may facilitate SARS-CoV-2 entry and processing, thereby contributing to COVID-19 severity." (PMID 39205219, 2024). "Peptides derived from EEA1 were enriched in 11% of patients with severe COVID-19 pneumonia but not in patients with mild COVID-19." (PMID 36300623, 2022).
diabetes (2 papers, 2022 to 2023). "EEA1 gene is a candidate mutation for susceptibility to diabetes in the Japanese population, which has been confirmed by a genetic background of familial clustering of diabetes using genome-wide linkage analysis combined with exome sequencing." (PMID 36923118, 2023). "Following induction of diabetes, colocalization of EEA1 with glucagon (PCC 0.03 ± 0.07) or Stmn2 (PCC 0.04 ± 0.07) still remained very weak." (PMID 34923907, 2022).
fungal infection (2 papers, 2023 to 2025). "After A549 cell fungal infection, cell lysis, and ultracentrifugation, 13 fractions of 1 mL each were collected, submitted to Western blot, and the presence or not of α3 integrin, the early endosome marker EEA1, and the late endosome/lysosome marker LAMP-1 was analyzed." (PMID 37755020, 2023).
glioma (2 papers, 2014 to 2022). A benign or malignant brain and spinal cord tumor that arises from glial cells (astrocytes, oligodendrocytes, ependymal cells). "Immunostainings in glioma tissues demonstrated that the endocytosis-recycling molecules Rab11 and EEA-1 are highly expressed in the glioma cell line #2." (PMID 24489888, 2014). "Furthermore, the staining of cultured single glioma cells also showed a high rate of co-localization of PDGFRA to Rab11 and to EEA-1." (PMID 24489888, 2014).
hepatoma (2 papers, 2012 to 2018). "Immunofluorescence studies indicate the LRP1-dependent trapping of apoE in EEA1-positive endosomes in human hepatoma cells." (PMID 22238606, 2012).
influenza (2 papers, 2016 to 2017). An acute viral infection of the respiratory tract, occurring in isolated cases, in epidemics, or in pandemics; it is caused by serologically different strains of viruses (influenzaviruses) designated A, B, and C, has a 3-day incubation period, and usually lasts for 3 to 10 days. "We confirmed that HIV traffics to early endosomal (EEA1) compartments by 18 hours as previously shown, whereas influenza and HA-HIV traffic significantly less to these compartments and the green signal is faded at 18 hours." (PMID 27082754, 2016). "NOX2 co-located with EEA1 in control and influenza infected cells." (PMID 28701733, 2017).
lung carcinoma (2 papers, 2022 to 2024). "To clarify whether Rab37 was involved in the endo-lysosomal trafficking pathway in our study, we analyzed the endosomal marker (EEA1) in purified autophagosomes under starvation conditions in lung cancer cells." (PMID 36457117, 2022).
lupus (2 papers, 2022 to 2025). "Interestingly, similarly to anti-IFN antibodies, anti-EEA1 antibodies have also previously been reported in the setting of systemic lupus erythematosus." (PMID 36300623, 2022).
melanoma (2 papers, 2014). A malignant, usually aggressive tumor composed of atypical, neoplastic melanocytes. "Thus, we found down-regulation of the TYRP1 gene, a melanocyte differentiation marker and over expression of MFI2 gene, a cell-surface glycoprotein playing a role in melanoma cell proliferation and tumorigenesis and EEA1 gene, a marker of early endosomes." (PMID 24742402, 2014).
acute leukemia (1 paper, 2023). A clonal (malignant) hematopoietic disorder with an acute onset, affecting the bone marrow and the peripheral blood. "ASC-deficient THP-1 cells, a human acute leukemia monocytic cell line, and immortalized mouse bone marrow-derived macrophages (iBMDMs) lacking ASC also showed PI4P distribution to EEA1-positive vesicles upon nigericin or CL097 treatment." (PMID 36443515, 2023).
acute pancreatitis (1 paper, 2017). An acute inflammatory process that leads to necrosis of the pancreatic parenchyma. "Although the EEA1 signals were very low in wild mouse pancreatic acinar cells in caerulein-induced acute pancreatitis (arrowheads), these signals rarely colocalized with LC3-positive vacuoles (arrow heads)." (PMID 28588238, 2017). "Interestingly, our present data showed that EEA1 is colocalized with LC3-positive vacuoles formed in Rab7Δpan pancreatic acinar cells during acute pancreatitis." (PMID 28588238, 2017).
amyloid (1 paper, 2023). "In conclusion, we observed enlarged EEA1 positive puncta volume, a hallmark of endosomal alterations, in AD patients, particularly at the dementia stage of the disease, that tend to correlate with amyloid load and cognition, therefore showing potential as biomarkers for AD." (PMID 36788216, 2023). "Since we observed correlations between the volume of EEA1 positive puncta in fibroblasts of AD patients and amyloid deposition in the brain, we then evaluated whether the median EEA1 positive puncta volume correlated with cognitive measures." (PMID 36788216, 2023).
autoimmune disease (1 paper, 2019). A disorder resulting from loss of function or tissue destruction of an organ or multiple organs, arising from humoral or cellular immune responses of the individual to their own tissue constituents. "EEA1 release into a pro-inflammatory environment with IL-1β could promote the initiation of autoimmune diseases." (PMID 30962463, 2019). "During this process, EEA1 release could be important for the development of autoimmune diseases." (PMID 30962463, 2019).
cognitive decline (1 paper, 2023). "The fact that EEA1 positive puncta volume also correlates to changes in cognition during the time interval preceding the skin biopsy reveals potential utility to predict cognitive decline that will need to be further validated in prospective cohorts." (PMID 36788216, 2023). "Therefore, it could be interesting to further study the correlations between EEA1 positive puncta volume and cognitive and neuroimaging markers, especially its potential predictive power on amyloid and tau pathology and cognitive decline." (PMID 36788216, 2023).
cyst (1 paper, 2016). A sac-like closed membranous structure that may be empty or contain fluid or amorphous material. "As the WT cyst matured, EEA1/Vps35-labelled EE and Rab11a-labelled RE became spatially resolved in the apical cytoplasm." (PMID 26786190, 2016).
Down syndrome (1 paper, 2023). "Increased size of Rab5 positive or early endosome antigen 1 (EEA1) positive puncta, another early endosomal marker, have also been observed in pyramidal neurons in pre-AD and in Down syndrome (DS), before amyloid deposition." (PMID 36788216, 2023).
edema (1 paper, 2020). An abnormal accumulation of fluid beneath the skin, or in one or more cavities of the body. "In pathophysiologic conditions, i.e., in the ischemic brain edema, AQP4 is shown to internalize and colocalize with early ensodome marker EEA1, as was demonstrated in rat brain sections." (PMID 32192013, 2020).
endothelial dysfunction (1 paper, 2019). In vascular diseases, endothelial dysfunction is a systemic pathological state of the endothelium (the inner lining of blood vessels) and can be broadly defined as an imbalance between vasodilating and vasoconstricting substances produced by (or acting on) the endothelium. "Inhibiting Cav-1, clathrin, or EEA1 using siRNAs against these components led to the recovery of PM-localized KCa2.3 and KCa3.1 levels, suggesting that siRNAs against these components can be used to treat endothelial dysfunction." (PMID 31871552, 2019).
Fabry disease (1 paper, 2019). Fabry disease (FD) is a progressive, inherited, multisystemic lysosomal storage disease characterized by specific neurological, cutaneous, renal, cardiovascular, cochleo-vestibular and cerebrovascular manifestations. "The small GTPases Rab5 and EEA1 play a rate-limiting role in membrane docking or fusion in the early endocytic pathway, and our previous study suggested that KCa3.1 is transported into early endosomes via a Rab5c- and EEA1-dependent process in Fabry disease." (PMID 31871552, 2019). "Previously, we demonstrated that PM KCa3.1 proteins are internalized via a clathrin-dependent process and transported in a Rab5c- and EEA1-dependent process in Fabry disease." (PMID 31871552, 2019). "Clathrin-dependent internalization, Rab5c, early endosome antigen-1- (EEA1-) dependent transportation, and lysosomal degradation were involved in globotriaosylceramide-induced KCa3.1 downregulation in Fabry disease." (PMID 31871552, 2019).
gastric cancer (1 paper, 2011). A primary or metastatic malignant neoplasm involving the stomach. "While the mechanism connecting CagA and EEA1 acquisition is unclear, there is an epidemiological association between bacterial strains that produce CagA and the more severe H. pylori disease outcomes, such as gastric cancer." (PMID 21426584, 2011).
glioblastoma (1 paper, 2023). The most malignant astrocytic tumor (WHO grade IV). "As a further test, we performed NEK6/7 siRNA knockdown in glioblastoma cells and observed an increase in the size of EEA1-marked vesicles after depletion of NEK7 but not NEK6, suggesting cell type–specific requirements for NEK functions." (PMID 37099601, 2023).
HCMV infection (1 paper, 2018). "However, during HCMV infection, CD59 accumulated in the SE as indicated by the increased association with EEA1 over time postuptake." (PMID 30042195, 2018). "HCMV infection hijacks cargo sorting into EEA1 or ARF6 membranes in heterotypic SEs." (PMID 30042195, 2018). "To determine if CIE cargos are differentially sorted into different vesicular domains of the ARF6+/EEA1− heterotypic SEs in HCMV infection, we exploited the ability of TRE17 to induce dissociation of ARF6 and EEA1 membranes into distinct populations." (PMID 30042195, 2018). "Therefore, we propose a model whereby HCMV infection directs the sorting of cargo, such as MHC-I and CD98, from ARF6-positive domains into EEA1-positive domains in heterotypic SEs, which accumulate during infection." (PMID 30042195, 2018).
neuroblastoma (1 paper, 2007). Neuroblastoma (NB) is the most common solid, extracranial childhood tumor. "In a differentiated human neuroblastoma cell line (SH-SY5Y), endogenous ClC-6 colocalizes with LAMP-1, a late endosomal/lysosomal marker, but not with early/recycling endosomal markers such as EEA-1 and transferrin receptor." (PMID 17534424, 2007).
osteosarcoma (1 paper, 2020). A usually aggressive malignant bone-forming mesenchymal neoplasm, predominantly affecting adolescents and young adults. "Furthermore, this striking effect on EEA1-positive endosomes could be recapitulated in an independent cell line, namely in U-2 OS osteosarcoma cells, further supporting this phenotype as being specific." (PMID 32354068, 2020).
polyarthritis (1 paper, 2019). "Autoantibodies to EEA1 have been described in patients with subacute cutaneous systemic lupus erythematosus, polyarthritis, rheumatoid arthritis, and neurological diseases." (PMID 30962463, 2019).
Sepsis (1 paper, 2024). Sepsis is defined as life-threatening organ dysfunction caused by a dysregulated host response to infection. "Heatmaps revealed that the expression levels of CD63, CD9, CD81, Tsg101, EEA1, Rab5, and Rab7 in lung macrophages were significantly higher than those in neutrophils in the healthy control sEV group and sEVs from patients with sepsis." (PMID 38910259, 2024).
Splenomegaly (1 paper, 2021). Abnormal increased size of the spleen. "Interestingly, the patient with the EEA1-PDGFRB transcript fusion was suffering from a HES with skin lesions and splenomegaly, which fully resolved after imatinib initiation." (PMID 33880432, 2021).
triple-negative breast carcinoma (1 paper, 2024). An invasive breast carcinoma which is negative for expression of estrogen receptor (ER), progesterone receptor (PR), and human epidermal growth factor receptor 2 (HER2). "To determine the trafficking pathway followed by ECM components, we measured Matrigel colocalisation with an early endosomal marker, EEA1, and a late endosomal/lysosomal marker, LAMP2, in MDA-MB-231 triple-negative breast cancer cells." (PMID 39666682, 2024).